CILP2 (cartilage intermediate layer protein 2)
Diseases named in the same sentence as CILP2 in open-access papers (continued):
Sharing a sentence is not in itself a finding about the gene and the disease.
infection (1 paper, 2021). The state of being infected such as from the introduction of a foreign agent such as serum, vaccine, antigenic substance or organism. "The expression of Ciart, Per2, Cilp2, Tnmd, Col2a1, and Wif1 at each time point post-infection was significantly different from that observed in uninfected diaphragms (P < 0.0001)." (PMID 33648561, 2021).
CILP2 also shares sentences with these, for which no sentence is quoted: Alzheimer disease (2 papers); coronary artery disease (2); intervertebral disc disorders (2); asthma (1); Atrophy (1); B-cell CLL (1); breast carcinoma (1); chronic myeloid leukemia (1); colon adenocarcinoma (1); disc degeneration (1); esophageal cancer (1); esophageal squamous cell carcinoma (1); glioblastoma (1); gout (1); hepatic (1); Hypertension (1); hypertriglyceridemia (1); infarction (1); intervertebral disc degeneration (1); low grade glioma (1); lung carcinoma (1); melanoma (1); metabolic disorders (1); multiple myeloma (1); musculoskeletal disorders (1); neuroblastoma (1); non-small cell lung carcinoma (1); nonalcoholic fatty liver (1); Pan (1); paraganglioma (1).
A further 8 diseases each share a sentence with CILP2 in 1 paper.